TPR (translocated promoter region, nuclear basket protein)
Diseases named in the same sentence as TPR in open-access papers (continued):
Sharing a sentence is not in itself a finding about the gene and the disease.
tumor (continued). "To further isolate the contributions of tumor cell TPr and platelet TPr to the antimetastatic efficacy of ifetroban, we conducted additional studies in an experimental hematogenous model of metastasis lacking a primary tumor and using TBXA2R-deleted tumor cells." (PMID 41233835, 2025). "Moreover, the co-incubation of U46619 and ifetroban led to a similar reduction in platelet-tumor cell adhesion, confirming that ifetroban can inhibit TPr signaling and prevent platelet-tumor cell adhesion even in the presence of activating signals." (PMID 41233835, 2025). "By blocking TPr, ifetroban may enhance anti-tumor immunity by restoring the function of these immune cells." (PMID 41233835, 2025). "This comparison indicated that TPR mRNA was increased in tumor tissues." (PMID 34793452, 2021). "ZHFX3, BIRC6, Axin2, CPEB3 and TPR can regulate the proliferation and apoptosis of tumor cells." (PMID 35087829, 2021). "However, a study concerning the role of nucleoporin TPR upregulation within this tumour attracted the interest of researchers in regard to its connection with autophagy, given the existing correlation between TPR depletion and autophagy induction in HeLa cells." (PMID 33803216, 2021). "Similarly, in a xenograft mouse model, the downregulation of TPR prevents tumour growth." (PMID 33803216, 2021). "Three of the fusion partners among adults with CRC harboring an NTRK gene fusion tumor have been commonly reported in the literature, including TPM3::NTRK1, TPR::NTRK1, and LMNA::NTRK1." (PMID 38967220, 2024). "Compared with the cholesterogenic subgroup, the glycolytic subgroup had higher rates of DDR2 and TPR CNV and higher proliferation scores and MK167 expression levels, but a lower tumor purity proportion." (PMID 34384498, 2021). "In contrast, TPr inhibition with ifetroban reduced platelet-tumor cell adhesion in both the presence and absence of TPr stimulation by U46619." (PMID 41233835, 2025). "In these models, we observed that ifetroban reduces metastasis in the absence of a primary tumor and when TPr is deleted from tumor cells, further supporting the notion that ifetroban attenuates the supportive role of platelet TPr in the metastatic cascade." (PMID 41233835, 2025). "However, modulation of TPr/TXA2 signaling in endothelial cells and immune cells likely contribute to the multifaceted mechanism of ifetroban in preventing tumor metastasis as well." (PMID 41233835, 2025). "Furthermore, also upon shutdown of gene transcription in tumour cells, ZC3HC1 remained located at the NE, together with TPR." (PMID 34440706, 2021). "TPr inhibition in platelets appears to be a prominent mechanism of ifetroban’s antimetastatic activity, particularly since ifetroban prevents metastasis in the absence of a primary tumor or in TBXA2R deleted cells." (PMID 41233835, 2025). "Therefore, the blockade of platelet TPr by ifetroban is primarily responsible for reduced platelet-tumor cell interactions, and TPr blockade in tumor cells does not impact platelet-tumor cell adhesion." (PMID 41233835, 2025). "Moreover, treatment of mice with ifetroban potently inhibited metastasis in the absence of a primary tumor and when TPr was deleted from tumor cells, suggesting that platelet TPr inhibition was responsible for the antimetastatic efficacy observed of ifetroban." (PMID 41233835, 2025). "Both TPR and DNAJC9 might have dual function in term of tumour biology." (PMID 36420261, 2022). "Enhanced growth of TPR-MET tumor may be explained not only by the increased proliferation and decreased apoptosis, but also by infiltration of murine neutrophils to those tumors, what is demonstrated by Ly6G/6C staining of tumor sections." (PMID 26384300, 2015).
tumor (continued). "In our model constitutive activation of MET signaling pathways blocked differentiation of the tumor cells in vivo, as TPR-MET tumors were formed by pleomorphic cells that did not shape into muscle fiber-like structures and were characterized by more undifferentiated morphology." (PMID 26384300, 2015).
infection (4 papers, 2022 to 2024). The state of being infected such as from the introduction of a foreign agent such as serum, vaccine, antigenic substance or organism. "Similar results were demonstrated upon overexpression of NXF1 or TPR, which connects viral mRNA to the nuclear pore complex, further demonstrating that nuclear export is a limiting step during infection." (PMID 36542656, 2022). "When interrogating the Vis AD cell proteome for proteins involved in the “interferon signaling” pathway, we found seven proteins altered by infection with CoV-2(P.1), among which five were upregulated (i.e., IRF1, HLA-C, TPR, EIF4G1, and TRIM28)." (PMID 36175400, 2022). "In contrast, we found six proteins altered by infection with CoV-2(B), among which five were downregulated (i.e., STAT1, HLA-E, TPR, TRIM25, and TRIM28)." (PMID 36175400, 2022).
CNS tumors (1 paper, 2024). "Six different ROS1 fusion partners have already been described in pediatric CNS tumors (+/−7% of pediatric CNS tumors): GOPC, ARCN1, CHCHD3, ZCCHC8, TPR and CEP85L." (PMID 39409964, 2024).
TPR also shares sentences with these, for which no sentence is quoted: acute lymphoblastic leukemia (1 paper); acute respiratory distress syndrome (1); amyotrophic lateral sclerosis (1); Arterial thrombosis (1); asthma (1); autoimmune disease (1); chronic lymphocytic thyroiditis (1); hematological malignancies (1); male infertility (1); melanoma (1); osteosarcoma (1); peripheral artery disease (1); serous ovarian carcinoma (1); virus infection (1).